BCL2 (BCL2 apoptosis regulator)
Description:
Suppresses apoptosis in a variety of cell systems including factor-dependent lymphohematopoietic and neural cells. Regulates cell death by controlling the mitochondrial membrane permeability. Appears to function in a feedback loop system with caspases. Inhibits caspase activity either by preventing the release of cytochrome c from the mitochondria and/or by binding to the apoptosis-activating factor (APAF-1). Also acts as an inhibitor of autophagy: interacts with BECN1 and AMBRA1 during non-starvation conditions and inhibits their autophagy function. May attenuate inflammation by impairing NLRP1-inflammasome activation, hence CASP1 activation and IL1B release.
Synonyms: Bcl-2; PPP1R50
Tractability: Small molecule: an approved drug acts on it; a structure with a bound ligand is known; a high-quality ligand is known; it belongs to a druggable protein family. Antibody: UniProt predicts a signal peptide or a membrane-spanning region. PROTAC: it is named in the literature on targeted protein degradation; UniProt records ubiquitination sites on it; ubiquitination databases record sites on it; its protein half-life has been measured; a small molecule that binds it is known. Other modalities: a drug acting on it is in phase 2 or 3 trials.
Target class: Ion channel; Other ion channel; Bcl-2 family; Miscellaneous ion channel
Chemical probes: A-1211212 (high quality), PD134508, PD134510, PD134512, PD134514, PD134516, PD134518, VENETOCLAX (high quality)
Safety:
Unwanted effects reported when the protein is acted on. In parentheses: how it was acted on, where the effect was seen, and who reports it.
neurotoxicity (source: ClinPGx)
Gene: Protein-coding gene on chromosome 18 (63,123,346 to 63,320,128, reverse strand). Ensembl gene ENSG00000171791.
Subcellular location: Mitochondrion outer membrane; Nucleus membrane; Endoplasmic reticulum membrane; Cytoplasm
Subcellular location (Human Protein Atlas): Mitochondria
Pathways (Reactome):
Immune System: Interleukin-4 and Interleukin-13 signaling; The NLRP1 inflammasome
Programmed Cell Death: Activation of BAD and translocation to mitochondria; BH3-only proteins associate with and inactivate anti-apoptotic BCL-2 members
Signal Transduction: Estrogen-dependent gene expression; Estrogen-dependent nuclear events downstream of ESR-membrane signaling
Cellular responses to stimuli: NFE2L2 regulating tumorigenic genes
Developmental Biology: Regulation of MITF-M-dependent genes involved in apoptosis
Gene Ontology:
Molecular function: BH3 domain binding; channel activity; channel inhibitor activity; DNA-binding transcription factor binding; identical protein binding; molecular adaptor activity; protease binding; protein binding; protein heterodimerization activity; sequence-specific DNA binding; ubiquitin protein ligase binding; protein phosphatase 2A binding; protein phosphatase binding
Biological process: apoptotic process; B cell proliferation; B cell receptor signaling pathway; defense response to virus; DNA damage response; extrinsic apoptotic signaling pathway via death domain receptors; intrinsic apoptotic signaling pathway in response to endoplasmic reticulum stress; negative regulation of anoikis; negative regulation of apoptotic process; negative regulation of apoptotic signaling pathway; negative regulation of autophagy; negative regulation of extrinsic apoptotic signaling pathway in absence of ligand; negative regulation of intrinsic apoptotic signaling pathway; negative regulation of neuron apoptotic process; positive regulation of B cell proliferation; positive regulation of cell growth; positive regulation of cell population proliferation; protein polyubiquitination; regulation of calcium ion transport; response to cytokine; response to iron ion; response to nicotine; response to toxic substance; response to xenobiotic stimulus; endoplasmic reticulum calcium ion homeostasis; and 22 more
Cellular component: BAD-BCL-2 complex; BCL-2 complex; cytoplasm; endoplasmic reticulum; endoplasmic reticulum membrane; membrane; mitochondrial outer membrane; mitochondrion; nuclear membrane; nucleus; pore complex; protein-containing complex; cytosol; mitochondrial membrane; myelin sheath
Genetic constraint (gnomAD): Loss-of-function variants: 1 observed, 12.88 expected, observed/expected ratio (o/e) 0.0776, 90% interval 0.027 to 0.37. The upper end of that interval is the gene's LOEUF score, 0.37, which puts it in group 1 of 6, group 1 being the genes least tolerant of losing a copy. Missense variants: 211 observed, 284.94 expected, observed/expected ratio (o/e) 0.74, 90% interval 0.66 to 0.83. Synonymous variants: 130 observed, 124.18 expected, observed/expected ratio (o/e) 1.05, 90% interval 0.91 to 1.21.
Homologues: Orthologues: chimpanzee BCL2 (100% identical), macaque BCL2 (99% identical), pig BCL2 (93% identical), dog BCL2 (91% identical), mouse Bcl2 (90% identical), rat Bcl2 (74% identical), guinea pig BCL2 (66% identical), tropical clawed frog bcl2 (65% identical), zebrafish bcl2a (45% identical), zebrafish bcl2b (42% identical). Paralogues in human: BCL2L1 (42% identical), BCL2L2 (33% identical), BAK1 (21% identical), MCL1 (21% identical), BAX (19% identical), BOK (18% identical), BCL2A1 (18% identical), BCL2L10 (15% identical).
Diseases named in the same sentence as BCL2 in open-access papers:
BCL2 is named in the same sentence as 968 diseases in open-access papers, as found by Europe PMC text mining. Sharing a sentence is not in itself a finding about the gene and the disease. The quoted sentences say what the papers report.
breast carcinoma (1,524 papers, 1994 to 2026). "This shift in the Bax/Bcl-2 ratio further tips the balance toward apoptosis, making breast cancer cells more susceptible to programmed cell death." (PMID 41496977, 2026). "BCL-2 is an anti-apoptotic gene, the expression of which can be used as a prognostic factor for breast cancer, and it is also thought to be associated with resistance to conventional cancer treatments." (PMID 40104496, 2025). "High BCL2 protein expression was also linked by others to improved disease-free survival in breast cancer." (PMID 40806359, 2025). "Previous studies have demonstrated that polysaccharides, such as guava seed polysaccharides (GSF3), can cause the apoptosis of MCF-7 breast cancer cells by increasing the Bax/Bcl-2 ratio." (PMID 40863621, 2025). "The BCL2 gene, encoding the anti-apoptotic Bcl-2 protein, is frequently overexpressed in breast cancer cells, a phenomenon attributed to the presence of 17β-estradiol." (PMID 41150756, 2025). "Increasing evidence indicates that overexpression of anti-apoptotic Bcl-2 family members, such as Bcl-2, Bcl-xL, and Mcl-1, is a major factor in breast cancer initiation, and is often associated with poor prognosis." (PMID 40949156, 2025). "This lends more credence to the theory that important apoptotic proteins, like Bcl-2 and Bax, are regulated by RA to cause apoptotic effects in breast cancer cells." (PMID 40427522, 2025). "miR-122-5p regulates anti-apoptotic and cell cycle proteins, such as Bcl-2, X-linked inhibitor of apoptosis proteins, and cyclin-dependent kinases (CDKs) in breast cancer." (PMID 41470858, 2025). "The findings indicate that 3-HBI reduces the growth of breast cancer by causing cell death, potentially by influencing the apoptosis pathway’s Bax, Bcl-2, and caspase-3." (PMID 41009343, 2025). "BCL2 is an anti-apoptotic protein and has been linked to the ER-α positive breast cancer subtype and was associated with favorable outcomes." (PMID 39890941, 2025). "MYC deregulation is involved in the development of a wide variety of cancers, BCL2 is dysregulated in many malignancies including breast cancer and gastric carcinoma, and NF-κB is implicated in numerous cancers." (PMID 38965209, 2024). "BCL-2 overexpression in breast cancer cells prevents apoptosis and is associated with neoplastic transformation and enhanced cellular survival." (PMID 38891056, 2024). "Focusing on the role of BAX and Bcl-2, these proteins are intricately linked to apoptosis and their expression carries prognostic implications in breast cancer." (PMID 38256428, 2024). "Breast cancer patients with a positive Bcl-2 protein expression are considered to have a better prognosis, and Bcl-2 is significantly associated with several favorable prognostic factors such as tumor size, ER and progesterone receptor positivity." (PMID 38167446, 2024). "Research has shown that a reduction in the anti-apoptotic protein BCL-2 (encoded by the bcl2a gene) can contribute to the development or progression of breast cancer." (PMID 39058170, 2024). "The apoptotic activity is mainly associated with the down-regulation of Bcl-2 expression in breast cancer cell lines." (PMID 38915036, 2024). "In glioma, lung, and breast cancer, Bcl-2 over-expression has been linked to an increase in invasion and migration." (PMID 38223131, 2024). "Proteins encoded by the bcl-2 gene family are critical for the regulation of apoptosis and are overexpressed in approximately 80% of breast cancer patients." (PMID 39502536, 2024). "In particular, using in vitro and in vivo preclinical cutaneous melanoma (hereafter melanoma) and breast carcinoma models we previously demonstrated Bcl-2 modulation of tumor progression-associated properties and tumor metastatization." (PMID 38755629, 2024). "The expression of Bcl-2 in breast cancer is also favorably linked with differentiated and prognostic markers, including ER/PR expression, slow proliferation, small tumor size, and HER2 negativity." (PMID 37736508, 2023).
breast carcinoma (continued). "Overexpression of Bcl-2 proteins such as Bcl2L10, also referred to as Nrh, is associated with resistance to therapy and poor survival in various cancers, including breast cancer, lung cancer, and leukemia." (PMID 37391438, 2023). "High expression of Bcl-2 remained strongly associated with breast cancer survival after an adjustment for race (HR 0.41, 95% CI 0.2, 0.85)." (PMID 37370761, 2023). "The expression of BCL-2 remained strongly positively associated with protection against breast cancer death, with an additional adjustment for age and ER+ or PR+ status (HR = 0.36, 95% CI 0.14, 0.92)." (PMID 37370761, 2023). "In contrast, there is also evidence that higher coffee consumption decreases breast cancer risk in postmenopausal and European women, women expressing the minor allele of the bcl-2 gene haplotype, and other bcl-2 polymorphisms." (PMID 36769029, 2023). "Increased expression of Bcl-2 was associated with a protective effect on breast cancer-specific survival (HR 0.32, 95% CI 0.16, 0.65)." (PMID 37370761, 2023). "Further down-regulation of Bcl-2 in tumor tissue is associated with more aggressive characteristics of breast cancer, such as later stages and higher grades at diagnosis." (PMID 37370761, 2023). "Adriamycin resistance in breast cancer cells has been shown to be associated with downregulation of Bcl‐2 expression and up-regulation of Bax expression." (PMID 37069240, 2023). "Many studies have clearly shown that an increase in BCL2 expression is associated with improved treatment in breast cancer." (PMID 38003498, 2023). "Our results are consistent with previous findings, which found that Bcl-2 expression was associated with a better prognosis for breast cancer despite its anti-apoptotic characteristic." (PMID 37370761, 2023). "In ductal breast carcinoma, the 1p36 deletion is associated with grade, ERBB2 loss, and loss of BCL2 expression and is known to be a common feature underlying breast cancer development and the carcinogenesis of various cancer types." (PMID 35992833, 2022). "As a mechanism for the activation of the Bcl-2 gene, chromosomal translocation has been shown to be associated not only with non-Hodgkin lymphomas but also with small cell lung cancer and breast cancer." (PMID 36355520, 2022). "Overexpression of IGFBP5 also causes breast cancer cells to undergo apoptosis by increasing Bax and decreasing Bcl-2, thus regulating the ability to resist cell death." (PMID 36465383, 2022). "In this study, using a PDX model of primary breast cancer combination therapy was associated with the release of Bim from Bcl-2 complexes and induction of cell death." (PMID 35053443, 2022). "Some reports have shown that females with BCL2 mutation have a three-times or higher risk of developing breast cancer than others." (PMID 36299777, 2022). "In one study, the combination of piperlongumine and docetaxel showed strong anticancer activity due to the suppression of various proliferative and apoptotic molecular markers associated with breast cancer, and the negative regulation of Bcl-2 and survivin." (PMID 35669542, 2022). "Bozovic-Spasojevic found that high expression of BCL2 is associated with a good prognosis of breast cancer." (PMID 35814404, 2022). "In a meta-analysis comprising 17 breast cancer studies, Bcl-2 was associated with improved disease-free survival (DFS) and overall survival (OS)." (PMID 35053443, 2022). "BCL2 is upregulated by estrogens in breast cancer, and its elevated expression has been associated with poor prognosis in luminal A breast cancer." (PMID 35200555, 2022). "BAD, Bcl-2-associated death promoter, modulates breast cancer cell proliferation and tumor progression by regulating cell cycle progression, sensitizes breast cancer cells to chemotherapy." (PMID 36199443, 2022).
breast carcinoma (continued). "This study is aimed at determining the association of XRCC3 Thr241Met (rs861539), XRCC4 G(-1394) T (rs6869366) DNA repair and BAX G(-248) A (rs4645878), and BCL2 C(-938) A (rs2279115) apoptotic gene polymorphisms with breast cancer." (PMID 35320970, 2022). "Bcl-2 has been shown to be an important prognostic marker in breast cancer patients and is associated with a favorable outcome." (PMID 35053443, 2022). "The ANXA3 protein is linked to reduced disease development in breast cancer patients and plays a role in apoptosis regulation in vitro by altering the Bcl-2/Bax balance." (PMID 34571787, 2021). "Apoptosis requires cellular proteins from the B-cell lymphoma 2 (BCL-2) family linked to breast cancer." (PMID 35574508, 2021). "KDM7A encodes a dual histone demethylase capable of promoting Bcl-2 upregulation and thereby suppressing apoptotic cell death in breast cancer." (PMID 34661511, 2021). "The kaempferol caused a marked anti-cancer effect in MCF-7 breast cancer cell lines mediated by down-regulation of Bcl-2 expression, accompanied by the overexpression of Bax protein and thus produced apoptosis." (PMID 34768743, 2021). "STAT3 has been shown to upregulate cyclin D-1, c-myc, and bcl-2, leading to the prevention of breast cancer cells apoptosis, suggesting an association between STAT3 in cell cycle and survival." (PMID 34488773, 2021). "Regarding breast cancer subtype, high BCL2 expression was associated with higher disease-free survival in the HRc(+)/HER2(−) subtype only (p = 0.001)." (PMID 34099764, 2021). "This suggests this new approach as particularly promising for ER+ breast cancer, as this subtype in particular is associated with strong BCL-2 overexpression." (PMID 34063475, 2021). "The association of BCL1 and BCL2 expression with various clinicopathologic features as well as different breast cancer subtypes was also investigated." (PMID 34099764, 2021). "The expression of Bcl-2 in human breast cancer is associated with a good prognosis, and ongoing studies have shown that destroying Bcl-2 can cause cell death." (PMID 33778070, 2021). "Studies have found that microRNA-195 can target BCL-2 to trigger mitochondrial dysfunction and then cause apoptosis, thereby enhancing the therapeutic efficacy of the chemotherapy drug etoposide in breast cancer." (PMID 33816265, 2021). "Amplification of MCL-1 is more frequent in clinical breast cancer datasets than BCL-2 and BCL-xL, and is associated with poor prognosis." (PMID 33883020, 2021). "In parallel, our data also demonstrate that high consecrations of EA trigger apoptosis, particularly in breast cancer cells, which is associated with Bcl-2/Bax/caspase-3 signaling pathway in HER2-positive cancer cells." (PMID 32947764, 2020). "It has also been displayed that BCL2 upregulation was associated with cisplatin-resistance in bladder, ovarian, lung, and breast cancer." (PMID 32660222, 2020). "We previously identified the Bcl-2-associated death promoter (BAD) as a prognostic indicator of good outcome in taxane-treated breast cancer patients." (PMID 31942016, 2020). "In this study, cinnamon caused a significant increase in the Bax/Bcl-2 ratio, which correlated with an increase in caspase-3 expression in treated mammary tumors in rats." (PMID 32204409, 2020). "The low or decrease in Bcl-2 expression is associated with treatment response in human breast cancer studies, similar to the lack or low Bax expression from 5-FU-based adjuvant therapies in human colorectal carcinoma." (PMID 31620453, 2019). "The biological mechanisms underlying the prognostic role of Bcl-2 in human breast cancer remain mysterious and largely uncertain." (PMID 30630524, 2019).